RN7SKP216 (RN7SK pseudogene 216)
Gene: Miscellaneous RNA gene on chromosome 12 (114,504,876 to 114,505,187, reverse strand). Ensembl gene ENSG00000222982.
Homologues: Orthologues: chimpanzee 7SK (99% identical), mouse Gm55407 (51% identical), guinea pig 7SK (35% identical). Paralogues in human: RN7SKP176 (71% identical), RN7SKP71 (71% identical), RN7SKP133 (70% identical), RN7SKP243 (70% identical), RN7SKP47 (70% identical), 7SK (70% identical), RN7SKP153 (70% identical), RN7SKP78 (70% identical), RN7SKP90 (70% identical), RN7SKP269 (69% identical), RN7SKP6 (69% identical), RN7SKP163 (69% identical), and 284 more.